MALAT1 (metastasis associated lung adenocarcinoma transcript 1)
Diseases named in the same sentence as MALAT1 in open-access papers (continued):
Sharing a sentence is not in itself a finding about the gene and the disease.
breast cancer (376 papers, 2009 to 2026). A primary or metastatic malignant neoplasm involving the breast. "The dysregulation of MALAT1 has been linked to poor prognosis in breast cancer, where its upregulation activates oncogenic pathways such as PI3K/AKT, Wnt/β‐catenin, and STAT3, leading to increased proliferation, survival, and therapeutic evasion." (PMID 41031251, 2025). "Metastasis Associated Lung Adenocarcinoma Transcript 1 (MALAT1) is a genic, nuclear lncRNA strongly correlated with tumor progression and metastasis in a wide variety of cancers, including breast cancer." (PMID 41181715, 2025). "MALAT1 overexpression is linked with a poor cancer prognosis, including in breast cancer, non-small-cell lung cancer, and glioma." (PMID 38674413, 2024). "Taken together with the results from the B16F1 model, these findings collectively suggest that loss of Malat1 in host mice exacerbates metastatic bone colonization by melanoma and breast cancer cells." (PMID 38493144, 2024). "In breast cancer tissues, elevated MALAT1 levels are associated with disease progression, and exosomal MALAT1 induces cell proliferation." (PMID 39401197, 2024). "MiR-497-5p has the potential to make breast cancer cells more susceptible to the effects of paclitaxel by blocking both MALAT-1 and SHOC2." (PMID 38511067, 2024). "lncRNA Malat1 is a well-known non-coding RNA associated with proliferation, migration, neoangiogenesis, immunosuppression, and invasiveness in breast cancer." (PMID 39272802, 2024). "The potential of ASOs is illustrated by their effectiveness against HOTAIR and MALAT1, lncRNAs implicated in breast cancer metastasis and oncogenesis." (PMID 38505593, 2024). "Associated with hyperproliferation and metastasis, MALAT1 is not only highly expressed in lung cancer, but also regulate migration and invasion of breast cancer cells." (PMID 39479021, 2024). "We also examined the interaction terms associated with the lncRNA MALAT-1, which is among the best studied lncRNAs in breast cancer context." (PMID 38838009, 2024). "The abundant lncRNA MALAT1 has been associated with a poorly differentiated and aggressive phenotype of mammary carcinomas." (PMID 38862471, 2024). "Metastasis associated lung adenocarcinoma transcript 1 (MALAT1) is a hypoxia-responsive lncRNA that promotes proliferation and migration in breast cancer cells." (PMID 37583933, 2023). "MALAT1 was shown to belong to the group of genes of theluminal B breast cancer subtype: MALAT1 mutations areassociated with such clinicopathologic parameters as a high tumor grade andhigh Ki-67 expression level." (PMID 37538803, 2023). "For example, it was discovered that the overexpression of MALAT1 inhibited the metastasis of breast cancer, while the deficiency in MALAT1 expression induced the metastasis of breast cancer." (PMID 36934373, 2023). "MALAT1 expression has been frequently associated with a poor prognosis, metastasis and chemo- and radio-resistance in several human tumors and in breast cancer." (PMID 36901971, 2023). "High expression of MALAT1 is associated with short relapse-free survival in patients with ER+ breast cancer treated with tamoxifen." (PMID 36358625, 2022). "Sequencing of large cohorts of breast cancer tissue has revealed recurrent mutations in long non-coding genes including MALAT1 and NEAT1." (PMID 36153537, 2022). "Regulation of Rho/ROCK signaling by metastasis-associated lung adenocarcinoma transcript 1 (Malat1) has been described in both osteosarcoma and breast cancer." (PMID 35447891, 2022). "In fact, a gene can have different roles in different cancers, such as long non-coding RNA MALAT1 is up-regulated in non-small cell lung cancer, Breast Cancer, Osteosarcoma, is associated with poor prognosis, and promotes cancer progression." (PMID 35600372, 2022). "Overexpression of MALAT1 is associated with larger sized tumors and advanced breast cancer stage and poor outcome particularly in TNBC." (PMID 35096427, 2022).
breast cancer (continued). "Metastasis-associated lung adenocarcinoma transcript 1 (MALAT1) induced docetaxel resistance in breast cancer cells by decreasing the expression of miR-200b." (PMID 35682560, 2022). "Metastasis-associated lung adenocarcinoma transcript 1 (MALAT1) is a lncRNA that has been dysregulated in anti-estrogen therapy-resistant breast cancer." (PMID 36358625, 2022). "High expression of MALAT1 was suggested to be associated with a poor prognosis in breast cancer patients." (PMID 35096427, 2022). "Enhanced expression levels of LncRNA metastasis-associated lung adenocarcinoma transcript 1 (MALAT1) were found in breast cancer cells and secreted sEVs." (PMID 36212432, 2022). "Metastasis-associated transcriptome 1(MALAT-1) of lung adenocarcinoma, whose abnormal expression can not only affect the invasion and metastasis of breast cancer cells, but also affect the EMT of breast cancer cells by regulating PI3K-Akt signaling pathway." (PMID 34422811, 2021). "MALAT1, an adverse prognostic factor, up‐regulated expression of which is associated with cancer development and lymph node metastasis in breast cancer." (PMID 34164906, 2021). "By contrast, by analyzing multiple independent large datasets, MALAT1 have very recently been found to be down-regulated in human colorectal and breast cancer tissues, and low MALAT1 expression is associated with decreased patient survival." (PMID 32174966, 2020). "The lncRNA NEAT1 and MALAT1 are some of the most abundant cellular RNAs and the genes encoding them undergo recurrent mutation in breast cancer." (PMID 32527287, 2020). "Using RNA reverse transcription-associated trap sequencing (RAT-seq), MALAT1 was shown to increase proliferation and migration of breast cancer cells via binding to the EEF1A1 promoter and upregulating its expression epigenetically." (PMID 32503170, 2020). "Metastasis associated lung adenocarcinoma transcript 1 (MALAT1) is involved in frequent tumours including renal cell carcinoma, bladder cancer, prostate cancer, breast cancer and so on." (PMID 32203053, 2020). "In breast cancer, the knockdown of metastasis-associated lung adenocarcinoma transcript 1 in a mouse model of breast cancer results in the slow growth of tumors and the loss of their metastatic ability." (PMID 32922184, 2020). "The association between MALAT-1 and poor prognosis in patients with breast cancer was consistent in most of the original studies as well as in the reprocessed data obtained from TCGA database." (PMID 32700729, 2020). "To further explore the possible reason why MALAT-1 is responsible for poor survival in patients with breast cancer, we analyzed the association between MALAT-1 and tumor infiltrating immune cells based on TCGA dataset." (PMID 32700729, 2020). "For instance, lncRNA MALAT1 (metastasis-associated lung adenocarcinoma transcript 1) overexpression inhibits the metastasis of breast cancer through regulating the pro-metastatic transcription factor TEAD." (PMID 33111744, 2020). "Metastasis-associated lung adenocarcinoma transcript 1 (MALAT1) is a lincRNA that has been suggested to be involved in the tamoxifen resistance of breast cancer." (PMID 32486413, 2020).
breast cancer (continued). "Malat1 is an evolutionarily conserved and abundant lncRNA that has been associated with breast cancer progression and metastasis." (PMID 31863590, 2020). "MALAT-1 also contributes to the maintenance of stem cell-like phenotypes in breast cancer cells by regulating self-renewal-associated factors." (PMID 32700729, 2020). "These discrepant findings encourage more studies to understand better the role of MALAT1 in breast cancer and the underlying molecular mechanisms associated with metastases." (PMID 32708561, 2020). "In the current study, a meta-analysis was conducted to clarify the association between MALAT-1 and the prognosis and clinicopathological features of breast cancer." (PMID 32700729, 2020). "MALAT1 is a metastasis-suppressing lncRNA that is highly expressed in breast cancer tissues and is associated with disease progression." (PMID 33318294, 2020). "Elevated expression of MALAT1 has been shown in breast cancer tissues and was associated with lymph node metastasis and poor disease outcome as well." (PMID 32708561, 2020). "On the one hand increased expression of MALAT1 is associated with relapse and metastatic progression in breast cancer." (PMID 31744046, 2019). "Previous studies conducted in Chinese populations also showed that the AG, GG genotype or G allele of MALAT1 rs619586 polymorphism was significantly associated with a decreased risk of breast cancer, CRC, ESCC, and PTC." (PMID 31500187, 2019). "In this paper, we discussed how the expression level of MALAT1 was associated with metastasis of breast cancer and prognosis of patients." (PMID 29416769, 2018). "The results suggested that MALAT1 showed varying expression levels in different subtypes of breast cancer, which was closely associated with metastasis of breast cancer and patients’ prognosis." (PMID 29416769, 2018). "In a mouse mammary carcinoma model, genetic loss or systematic depletion of MALAT1 in MMTV-PyMT resulted in slower tumor growth and reduction in metastasis." (PMID 30496290, 2018). "MiR-1 binding with CDC42 (mediated by MALAT1) induced migration and invasion of breast cancer cells and CDC42 activity has been implicated in the invasive phenotype." (PMID 28589855, 2017). "The long non-coding RNA MALAT1 has been implicated in several cancers; however, its role in breast cancer is still little known." (PMID 27172249, 2016). "Downregulation of MALAT1 (long noncoding RNA metastasis-associated lung adenocarcinoma transcript 1) inhibits breast cancer cell proliferation and cell cycle progression in vitro and in vivo through miR-124 downregulation and CDK4 upregulation." (PMID 27818681, 2016). "The novelty of our work resides in the identification of a new estrogen-dependent association between HOTAIR/MALAT1 and ERβ/ERα (in prostate or breast cancer cells, respectively) and/or eNOS." (PMID 27922078, 2016). "For example, whole genome analysis revealed clustered mutations in MALAT1, suggesting a gain-of-function role for this poorly understood and abundant lncRNA in breast cancer." (PMID 25606588, 2014). "Additionally, MALAT1 has been associated with promoting aggressive breast cancer (BC) by inducing overexpression of MALAT1 and simultaneous downregulation of hsa-miR-448." (PMID 39323624, 2024). "We have identified some lncRNAs associated with breast cancer cell subpopulations already well known in the literature, such as MALAT1 and NEAT1, and highlighted some others that may be clinically relevant." (PMID 38611028, 2024). "Besides, lncRNA MALAT1 level has also been confirmed to be associated with lymphatic metastasis in breast cancer." (PMID 38956558, 2024). "In addition, synergism of TALAM1 with Metastasis Associated Lung Adenocarcinoma Transcript 1 (MALAT1) was evidenced in the tumor characteristics and acquisition of aggressiveness of breast cancer." (PMID 37754231, 2023). "Notably, high expression of METTL3 and MALAT1 in breast cancer has been associated with poor prognosis." (PMID 37369946, 2023).
breast cancer (continued). "MALAT1 deletions and highfrequency of insertion and deletion mutations (that most likely had arisenduring transcription) were also observed in patients with the luminal subtypesof breast cancer." (PMID 37538803, 2023). "These biological functions may explain the association of MALAT1 levels with the decreased ability of breast cancer to progress and metastasize." (PMID 35592755, 2022). "Interestingly, previous bioinformatics analysis studies suggested that MALAT1 was associated with a poor prognosis of breast cancer." (PMID 35585970, 2022). "Although some previous studies have investigated the associations of lncRNA MALAT1 rs3200401, rs619586 and rs1194338 with breast cancer, 22 colorectal cancer 23 and esophageal cancers, 24 to date no research explores the relationships between these SNPs and CC." (PMID 35517413, 2022). "As the first lncRNA found to be associated with metastasis, metastasis‐associated lung adenocarcinoma transcript 1 (MALAT1) has been shown to be associated with poor prognosis of lung cancer and breast cancer, and its expression is significantly increased in patients with metastatic cancer." (PMID 34977870, 2021). "In addition, serum MALAT1 has proven its diagnostic value for breast cancer (sensitivity 83.7%; specificity 81.2%)." (PMID 34527584, 2021). "In both genetically engineered mouse models and xenograft models, lncRNA MALAT1 overexpression inhibits, while MALAT1 deficiency induces breast cancer metastasis, which is reversed by re-expression of MALAT1, suggesting that MALAT1 is a metastasis-suppressing lncRNA." (PMID 34497807, 2021). "Malat1 is frequently mutated in breast cancer and has important roles in breast cancer metastasis." (PMID 31863590, 2020). "Importantly, one of the identified TROLLs was MALAT1, previously demonstrated to promote different metastatic tumour types in humans, including breast cancer where high levels of this lncRNA correlate with higher risk of relapse and reduced overall survival." (PMID 33056990, 2020). "High expression of MALAT1 in breast cancer cases and may be associated with triple-negative breast cancer (TNBC)." (PMID 32708561, 2020). "In addition, MALAT1 overexpression has been shown to be associated with drug resistance in breast cancer, CRC, prostate cancer, etc.." (PMID 32503170, 2020). "Therefore, further studies should be conducted to identify the function of MALAT-1 in breast cancer and verify the association between clinical parameters and MALAT-1 expression." (PMID 32700729, 2020). "Therefore, we conducted a systematic review to investigate the associations of MALAT-1 with clinicopathological features and survival of patients with breast cancer." (PMID 32700729, 2020). "Furthermore, somatic mutations in MALAT1 have been so far identified in women with breast cancer (luminal-type) and its depletion in luminal cells from ER+ tumors has been reported to dramatically restrain tumor cells’ proliferation." (PMID 33142861, 2020). "Importantly, compared with control PyMT mouse mammary tumors, MALAT1-deficient PyMT mouse mammary tumors exhibit increased TEAD target gene expression and tumor metastasis, which can be reversed by genetic MALAT1 add-back." (PMID 32174966, 2020). "The upregulation of MALAT1 may play an essential role in breast cancer development and associated with lymph node metastasis." (PMID 32708561, 2020). "MALAT1 expression in breast cancer was associated with lymph metastasis." (PMID 32708561, 2020). "In addition, loss of MALAT1 in the mouse mammary tumor virus (MMTV)-PyMT mammary carcinoma mice results in alterations in the expression and splicing of genes important for cell differentiation and tumorigenesis." (PMID 32174966, 2020). "Furthermore, the lncRNA MALAT1 rs619586 and rs3200401 variants are associated with a decreased susceptibility to breast cancer." (PMID 31024342, 2019).
breast cancer (continued). "We predicted that 18 miRNAs associated with breast cancer might potentially exert regulatory functions on MALAT1 when the minimum folding free energy was set under ≤25 and the system score was set to >160." (PMID 30683807, 2019). "Overexpression of metastasis associated in lung adenocarcinoma transcript 1 (MALAT1) is associated with poor prognosis in tamoxifen-treated ER+ breast cancer patients, and might be considered as a potential biomarker to predict endocrine treatment sensitivity." (PMID 28959047, 2017). "MALAT1 is a tightly regulated and multifunctional lncRNA, which controls key gene networks by fine-tuning both transcription and alternative splicing of specific cancer-associated genes in different subtypes of breast cancer cells." (PMID 27250026, 2016). "Furthermore, of 204 breast cancer patients, high MALAT1 expression was associated with positive ER (P = 0.023) and progesterone receptor (PR) (P = 0.024) status." (PMID 27191888, 2016). "Mutations and deletions in the human MALAT1 gene were recently discovered in luminal breast cancer." (PMID 27191888, 2016). "Assessment of the prognostic significance of MALAT1 in human breast cancer (n=1992) revealed elevated MALAT1 expression was associated with decreased disease-specific survival in ER negative, lymph node negative patients of the HER2 and TNBC molecular subtypes." (PMID 27250026, 2016). "Indeed, several dysregulated lncRNAs, such as HOTAIR and MALAT-1, have been found to be associated with breast cancer survival." (PMID 26549855, 2015). "Despite these limitations, the present study still demonstrated that MALAT1 signature was associated with patient survival, and might potentially be used as a new independent prognostic marker to predict the OS of breast cancer patients for diagnosis age below 60 or infiltrating ductal carcinoma." (PMID 30683807, 2019). "For another example, metastasis associated lung adenocarcinoma transcript 1 (MALAT1) has been shown to interact with serine/arginine (SR) proteins, modulate mRNA alternative splicing, and over-express in non-small-cell lung cancer, hepatocellular carcinomas and breast cancer." (PMID 30504132, 2019). "Then, the breast cancer cells were treated with actinomycin D to observe the stability of lncRNA MALAT1." (PMID 40258843, 2025). "In this respect, MALAT1 upregulation in breast cancer patients and cell lines has been recently correlated to low innate and adaptive immune response due, at least partially, to the interaction with miR-34a target." (PMID 40863726, 2025). "ISH staining of MALAT1 in HER2 positive breast cancer patients (n = 58) treated with trastuzumab showed that patients with high expression of MALAT1 were resistant to trastuzumab treatment." (PMID 40258843, 2025). "MALAT1 overexpression was observed in 70% of breast cancer patients (p < 0.001), with its highest levels in HER2-positive tumors." (PMID 40674376, 2025). "We compared MALAT1 expression between the MCF7 breast cancer cell line and the normal breast cell line MCF10 using qRT‐PCR." (PMID 41031251, 2025). "Our study highlights the promising role of NanoCurcumin in resensitizing tamoxifen‐resistant breast cancer by modulating epigenetic regulators such as MALAT1." (PMID 41031251, 2025). "These seemingly contradictory findings highlight the multifaceted nature of MALAT1’s function in breast cancer metastasis." (PMID 39997609, 2025). "qRT-PCR assays confirmed that MALAT1 also showed higher expression in breast cancer tissues than adjacent tissues." (PMID 40258843, 2025). "MALAT-1 ASOs were found to inhibit branching morphogenesis in a three-dimensional breast cancer organoid model." (PMID 39912974, 2025).